MKI67 (marker of proliferation Ki-67)
Diseases named in the same sentence as MKI67 in open-access papers (continued):
Sharing a sentence is not in itself a finding about the gene and the disease.
breast cancer (continued). "Amongst the other highly significant upregulated CR genes by p-value and log2FC, SKA2, MKI67, HJURP, BIRC5, and CCNB1 are upregulated in breast cancer tissues and all five except for SKA2 have been identified as prognostic markers for breast cancer." (PMID 32457901, 2020). "Mutant plectin (PLEC), marker Of Proliferation Ki-67 (MKI67), HEAT Repeat Containing 1 (HEATR1) and AHNAK nucleoprotein (AHNAK) were detected in three of the four breast cancer cell lines." (PMID 33274046, 2020). "Hierarchical clustering of NCS‐1 and breast cancer molecular markers showed a positive correlation with basal and proliferative markers, such as KRT5, 14 and 17, CDH3, FOXC1, FOXM1, EGFR, and MKI67." (PMID 31647602, 2020). "In recent years, proliferation marker Ki-67 (MKI67), which was firstly identified by Gerdes in the early 1980s28, was considered as a reliable marker in neoadjuvant settings of breast cancer." (PMID 31506496, 2019). "As expected, the expression of EPB41L4A-AS2 was negatively correlated with the expression of MKI67 and MYC both in breast cancer patients and the patients in the pancancer cohort." (PMID 30764831, 2019). "Ki‐67 (MKI67) is a marker of cellular proliferation 5 and can predict the prognosis of patients with cancer 6, including breast cancer." (PMID 29511610, 2018). "We also added genes important for breast cancer biology or subtyping (ER, PGR, ERBB2, MKI67, AURKA and FOXC1)." (PMID 29973242, 2018). "For muscle-invasive disease, the direct comparison of the breast cancer subtypes and bladder cancer subtypes has been shown and the four targeted genes ESR1, PGR, ERBB2 and MKI67 have been shown to be of diverse expression in bladder cancer." (PMID 28978063, 2017). "Training on public gene expression profiles of 995 breast cancer patients, this method prioritized one gene-set pair (GRHL2, CDH2, FN1, CITED2, MKI67 versus CTNNB1 and CTNNA3) from all 2717 possible gene-set pairs (GSPs)." (PMID 23441166, 2013). "AURKA, BIRC5, CCNB1, MKI67 and MYBL2 are well characterized genes involved in breast cancer proliferation." (PMID 22046260, 2011). "In addition, the CD4+_ISG15, CD4+_MKI67 and IFN-I signatures identified in tumor-infiltrating CD4+ T cells showed enrichment in the same tissue region in a human breast cancer specimen subjected to spatial transcriptomic profiling (10x Visium)." (PMID 38383773, 2024). "In a Europe-wide external quality assessment, we compared performance of an mRNA-based method [Xpert® Breast Cancer STRAT4 (CE-IVD)] for determining ESR1, PGR, ERBB2, and MKI67 expression against the gold standard [immunohistochemistry (IHC)/HER2 in situ hybridization (ISH)]." (PMID 34572945, 2021). "Kaplan–Meier analyses of overall and relapse-free survival in ER+/HER2+ breast cancer patients revealed that HK2 high-expressing tumors are characterized by worse prognosis, independently of HER2, ESR1 and proliferation status measured using MKI67 levels." (PMID 32164162, 2020). "Interestingly, the analysis of breast cancer datasets revealed that the expression of PICH correlates with that of mitosis-related genes, such as KIF4A, CEP55, MKI67, MELK, BUB1, CENPA, and AURKB." (PMID 31160555, 2019). "Further inspection of the modules found that three of these modules are related to known breast cancer related processes such as epithelium development, chromosome organization, and mitotic cell cycle including well-known breast cancers genes such as NCOA3, AURKA, MKI67, and FOXA1." (PMID 30906311, 2019). "This set comprised senescence markers (CDKN1A, LMNB1, MKI67), apoptosis regulators (BCL2, BCL2L1), a highly overexpressed gene (ITGB6), and drug targets (ACTA2, GSDMC, KRT6A, PDE1A, PSMA8), all of which showed strong concordance with our RNA-seq data in all four breast cancer cell lines." (PMID 40312750, 2025).
breast cancer (continued). "Breast cancer exhibits high heterogeneity and is clinically categorized into five intrinsic subtypes based on the expression of the estrogen receptor (ER), the progesterone receptor (PR), epidermal growth factor 2 (ERBB2), and the Ki67 proliferation marker protein (MKI67)." (PMID 39065193, 2024). "In clinical practice, the molecular subtyping of breast cancer (BC) relies on immunohistochemistry (IHC) to measure the protein expression of estrogen receptor ER/ESR1, progesterone receptor PR/PGR, human epidermal growth factor receptor 2 HER2/ERBB2, and marker of proliferation Ki67/MKI67." (PMID 38337757, 2024). "Standardized diagnostic evaluation based on hormone receptors (ER and PR) and HER-2 was essential to determine these subtypes and the histochemical staining of proliferation marker protein Ki-67 (MKI67) could be used to differentiate intracavity A-like and B-like breast cancer." (PMID 36249424, 2022). "This study addressed the question whether the recently developed molecular in vitro diagnostic MammaTyper® test could improve the reproducibility of the assessment of the four key routine breast cancer biomarkers ERBB2 (HER2), ESR1 (ER), PGR (PgR), and MKI67 (Ki67)." (PMID 28490348, 2017). "Besides, knockdown of MRC2 in human breast cancer cell lines: MCF7, MDA-MB-231, and MDA-MB-436 could also decelerate the cell proliferation, and reduce the mRNA levels of proliferation markers CCND1 and MKI67." (PMID 34815798, 2021). "Consequently, the major biological distinction between luminal A and B is the proliferation signature, which includes genes such as CCNB1, MKI67, and MYBL2, with higher expression in luminal B than in luminal A tumors and may be important to breast cancer biology and prognosis." (PMID 23368410, 2013). "Xpert Breast Cancer STRAT4 is a RT-qPCR platform that studies the mRNA expression of ESR1, PGR, MKI67 and ERBB2, providing a positive or negative result for each of these breast cancer biomarkers." (PMID 36980575, 2023). "In line with that, other breast cancer assays, like the GeneXpert Breast Cancer STRAT4 assay from Cepheid, that also measures the expression levels of ERBB2, ESR1, PGR and MKI67, found that macrodissection of whole tissue sections is not required for accurate assessment of these genes by RT-qPCR." (PMID 30342538, 2018). "Notably, although proliferative TAMs have been identified by proliferation indicator Ki-67 (MKI67) and cell cycle genes such as CDK1 in various cancer models, such TAMs were not previously identified in breast cancer due to various gene expression across cancer types." (PMID 39232806, 2024). "The second outcomes are clinicopathological parameters in breast cancer including the following items: histological grade; lymph node metastasis; The TNM classification of malignant tumors stage; the expression of HER-2, EGFR, estrogen receptor, PR, MKI67, cytokeratin 5/6." (PMID 30896652, 2019).
glioma (513 papers, 2004 to 2026). A benign or malignant brain and spinal cord tumor that arises from glial cells (astrocytes, oligodendrocytes, ependymal cells). "CENPF, TOP2A, UBE2C, PBK, and MKI67 were strongly expressed in glioma clusters, indicating the presence of progenitor cells." (PMID 39333557, 2024). "Cells positive to the general proliferative marker MKI67+ were present among both glioma cell phenotypes." (PMID 34692159, 2020). "Cancer proliferation and invasion genes were downregulated, including proliferation marker gene MKI67 with prognostic value in glioma, nerve growth factor receptor NGFR involved in GBM invasion, and long non-coding RNA MALAT1 with tumor suppressive function in GBM." (PMID 38177502, 2024). "Notably, single-cell analysis of CENPA showed that CENPA and MKI67 are expressed in the same type of cells, mainly in glioma cells, suggesting that the high expression of CENPA means that the cells are in an active proliferative state." (PMID 36341103, 2022). "Moreover, Sf3b1 expression was also significantly correlated with key glioma/spliceosome -markers (Mki67/Pdgfra/Rbm22/Sf3b1)." (PMID 35086552, 2022). "MKI67 is commonly used as a cell proliferation marker in the clinical management of glioma." (PMID 36341103, 2022). "Antigen Ki-67, also known as MKI67, is a cell-proliferative protein that encodes by the MKI67 gene and is widely used as a prognostic marker for several tumors, including glioma." (PMID 34066132, 2021). "Gliomasphere line specific (EGFR) and cell cycle markers (MKI67, TOP2A) dominated clustering and we noted enrichment of glioma stem cell (PTPRZ1, SOX2) and astrocytic markers (GFAP, S100B) in GS025." (PMID 38856710, 2024). "Scatter plots and bubble plots showed that MKI67 and CENPA were mainly co-expressed in glioma and stromal cells, which revealed that CENPA-expressing cells showed high proliferation." (PMID 36341103, 2022). "The level of expression glioma-characteristic genes (e.g. CD34, GFAP, OLIG2, MAP2, MKI67, RBFOX3, SOX2, SYN; Suppl." (PMID 34545083, 2021). "This is consistent with glioma database analyses showing that ETNPPL expression is inversely correlated to STAT3 and MKI67 whose expression are higher in foci and glioblastomas." (PMID 32218467, 2020). "Additionally, the mRNA expression levels of MST4/STK26, USP14, and ALKBH5 were positively correlated with ALKBH5 target genes, including FANCD2, FANCI, MKI67, and RAD51 within the TCGA and CGGA glioma datasets." (PMID 39990235, 2025). "Moreover, canonical oncogenic proliferation markers MKI67 and TOP2A were upregulated in the CDC20+KIF20A+PTTG1+ cell subpopulation of glioma samples." (PMID 40047299, 2025). "The expression of ZEB1 and vimentin as well as Ki-67 (MKI67) as proliferation marker, was increased in co-cultured glioma cells as compared to glioma cells cultured without LAD2 cells." (PMID 28445977, 2017).
lymph node metastasis (454 papers, 2005 to 2026). "The relationships between Ki-67/MKI67 expression, lymph node metastasis (LNM), vascular invasion (VI), and perineural invasion (PI) in esophageal squamous cell cancer (ESCC) remain unclear." (PMID 40028218, 2025).
melanoma (391 papers, 2005 to 2026). A malignant, usually aggressive tumor composed of atypical, neoplastic melanocytes. "As a result, the assay established the abundant expression of the melanoma marker gene SOX10 in the superficial melanoma region along with its co‐expression with the proliferation‐associated MKI67 (Figure S6A1)." (PMID 39846232, 2025). "The early stage of regeneration (1dpa) and melanoma is characterized by the upregulation of genes, including cdk2, mcm7, pcna, mki67, and cdk1, associated with proliferation and cell cycle." (PMID 38020918, 2023). "By use of CRISPR-Cas9 genome editing, we introduced sequences encoding EGFP at the endogenous locus of CDKN1B and sequences encoding mCherry at the endogenous locus of MKI67, into Mel-RM and A375 melanoma cells." (PMID 34646389, 2021). "In transdifferentiated A375 cells the melanoma markers MKI67, MITF, S100A4, S100A10, MMP2 and MMP9 were significantly downregulated." (PMID 40715046, 2025). "Phenotypically overlapping monocyte/macrophage subsets were found in the two tumor models, with “Mki67+ macrophages” in melanoma corresponding to Macro_5 and Macro_6 in MC38 tumors, and “IFN responsive monocytes” in melanoma corresponding to Mono_1 and Macro_3 in MC38 tumors." (PMID 40475851, 2025). "On the other hand, proliferation-related genes, including cdk2, minichromosome maintenance complex component 7 (mcm7), pcna, marker of proliferation Ki-67 (mki67), and cdk1 were upregulated in the melanoma tissues while being unaltered in nevi, when compared to the control." (PMID 38020918, 2023). "This was accompanied by the expression of proliferation marker Mki67 and exhaustion markers Pdcd1, Lag3, and Tim3 at the RNA level, which is consistent with reports of cell differentiation from naive cells, through a transitional state, toward dysfunction in human melanoma." (PMID 32433953, 2020). "Another subpopulation expressing high levels of MKI67 and STMN1 was classified as Mac_Prolif (n = 2234), and found to be enriched in liver, melanoma, and ovary tumor samples." (PMID 38972873, 2024). "In the melanoma cohort, PD-1 blockade responders (R) had significantly higher enrichment scores for the CD4+_MKI67 signature (p = 0.025) and the CD4+_CXCL13 signature (p = 0.05) than nonresponders (NR) did, indicating the predictive value of this cell population." (PMID 38383773, 2024). "In addition, we identified Mesenchyme (COL1A1+), Endothelium (SOX18+, KDR+), proliferating cells (TOP2A+, MKI67+), and some off‐target cells; Glial (MSX1+, SOX2+), Melanoma (PMEL+, PLP1+), and Neuron (DLL3, HES6)." (PMID 35322595, 2022).
breast tumors (277 papers, 1993 to 2026). "MKI67 (also called Ki67) has long been identified as a proliferation marker in breast tumor grading systems." (PMID 22956898, 2012). "Like MKI67, which encodes the proliferation-related antigen Ki-67, the expression of most of these genes (except CCNB3 and UBD) increased during the transition from grade I to ductal grade III breast tumors." (PMID 21352579, 2011). "MKI67 only showed significant overexpression in ductal carcinoma in situ (DCIS) and invasive ductal grade III breast tumors." (PMID 21352579, 2011). "The PR gene, PGR, and 3 other genes (GATA3, STC2 and GLI3) are increased in their expression, whereas the expression of 6 genes (AURKA, BUB1, CDC20, MKI67, HJURP, and CENPA) is decreased in PR-positive breast tumors." (PMID 22022496, 2011). "MKI67 and TERT were significantly upregulated in the 23 DNA aneuploid breast tumors, while ESR1/ERα expression was similar in the diploid and aneuploid breast tumor subgroups." (PMID 21352579, 2011). "Clusters of genes containing some of the most important known markers of breast tumour phenotype are shown in greater detail: ESR1, MKI67, ERBB2, and TFF1." (PMID 17555561, 2007). "Surprisingly, a significant link was observed between Δsv-MALAT1 underexpression and tumours with large macroscopic size, negative for HRs and expressing high MKI67 mRNA levels, suggesting that underexpression of Δsv-MALAT1 has a role in aggressiveness of breast tumours." (PMID 27172249, 2016).
neuroendocrine tumors (273 papers, 2006 to 2026). "The Ki-67 antigen is the product of the MKI67 gene related to cell proliferation, which has a value in discriminating pulmonary carcinoids from high-grade neuroendocrine tumors in small biopsies." (PMID 32923302, 2020).
lung carcinoma (253 papers, 1996 to 2026). "Potential biomarkers such as nuclear protein MKI67, which regulates the genes related to tumorigenesis, can predict lung cancer, as it is shared by both TB and lung adenocarcinoma." (PMID 35160218, 2022). "This study also revealed several up-regulated genes associated with lung cancer such as TOP2A and MKI67, and with tumor metastasis such as CDH11 and CD44." (PMID 34492061, 2021). "In these high MKI67IP-expressing cancer types, the most significant positive correlation between MKI67IP and MKI67 expression was detected in lung cancer (ρ = 0.488, p<0.001)." (PMID 26984280, 2016). "TCR tracking in liver cancer, lung cancer, and colorectal cancer has shown that Mki67-positive CD8+ T cells share the same TCR sequence (paired α and β chains) with those identified exhausted effector T cells with anti-tumor effects, suggesting that they have the same origin but different states." (PMID 38280084, 2024). "Also, Mmp9 and Mki67 were overexpressed in both lung cancers." (PMID 31921388, 2019). "qRT-PCR confirmed that the expression level of CDKN3, MKI67, CEP55, SPAG5, AURKA, TOP2A were highly expressed in lung cancer tissues." (PMID 35178291, 2022). "Meanwhile, at 8 weeks after PHMG exposure, lung cancer-related genes such as TOP2A and MKI67 and tumor metastasis-related genes such as CDH11 and CD44 were significantly upregulated." (PMID 33737587, 2021). "Functional classification analysis revealed that lung cancer-related genes, such as TOP2A and MKI67, and tumor metastasis-related genes, such as CDH11 and CD44, were significantly up-regulated after 8 weeks of PHMG exposure." (PMID 33737587, 2021). "At protein level, positive expression of MKI67 in NSCLC tumors while negative expressed in normal lung tissues was shown in HPA and MKI67 overexpression in NSCLC tumors was also confirmed in CPTAC lung cancer dataset (p < 0.01)." (PMID 32265992, 2020).
prostate carcinoma (237 papers, 2001 to 2026). A carcinoma that arises from epithelial cells of the prostate gland. "Our findings indicate that Ang1–7 (1 nM; 48 h) can effectively reduce cell proliferation only in DU-145 cells; however, a significant decrease in MKI67 expression was also observed in the case of an androgen-dependent prostate cancer cell line." (PMID 30361641, 2018). "Expression of DKC1 was measured by quantitative RT–PCR in prostate cancer tissues in relation to hTR and the proliferation marker MKI67." (PMID 19755982, 2009). "Ki67, a nuclear protein, coded for by the MKi67 gene located on chromosome 10q26.2 and detected in all phases of the cell cycle, provides information on the proliferation index of cancer cells, including prostate cancer." (PMID 40260342, 2025). "UBE2C, PDZ-binding kinase (PBK), cyclin B1 (CCNB1), Cyclin-dependent kinase inhibitor 3 (CDKN3), topoisomerase II alpha (TOP2A), Aurora kinase A (AURKA) and MKI67 were identified as the candidate hub genes, which were all correlated with prostate cancer patient’ disease-free survival in TCGA." (PMID 33630978, 2021). "Furthermore, our identification of prostate cancer-specific epithelial cell states, including the novel club cell population and proliferative MKI67+ epithelial cells in organoid cultures, offers potential models for testing drug responses and understanding tumor heterogeneity in vitro." (PMID 40943497, 2025). "The upregulated gene set included oncogenes such as PIK3CB, FGFRL1, and NCOA2; prostate cancer-related genes such as SPON2, PCAT4, and SCHLAP1; and cell cycle genes such as MKI67, MCM4, KIF4A, CENPF, and FLNB." (PMID 38067373, 2023). "CKS2, TK1, MKI67, TOP2A, CCNB1 and RRM2 directly related to the recurrence and prognosis of prostate cancer." (PMID 32266115, 2020). "To determine our prediction, we found CCNB1, CKS2, MKI67, RRM2, TK1 and TOP2A acted as independent prognostic factors in TCGA prostate cancer." (PMID 32266115, 2020). "Other genes associated with tumorigenesis of prostate cancer, such as ATM, MKI67, and SPOP, showed non-significant increases in somatic mutation frequency in the low-TICS group." (PMID 36918939, 2023). "The results showed that 7 genes were all associated with prostate cancer prognosis, but only UBE2C, TOP2A and CCNB1 were high expression in prostate cancer samples than normal prostate gland samples, the expression of PBK, CDKN3, AURKA, MKI67 were not." (PMID 33630978, 2021). "In prostate cancer tissues, a moderate and significant correlation has been observed between DKC1 and MKI67 mRNA levels, but not with PCNA mRNA." (PMID 22912812, 2012).